TTR (transthyretin)
Diseases named in the same sentence as TTR in open-access papers (continued):
Sharing a sentence is not in itself a finding about the gene and the disease.
cardiac amyloidosis (continued). "However, one of the most morbid manifestations of the disease is cardiac deposition causing a restrictive cardiomyopathy known as transthyretin amyloid cardiomyopathy, or ATTR-CM." (PMID 40943848, 2025). "The frequent association between transthyretin wild‐type (TTRwt) cardiac amyloidosis (CA) and aortic stenosis (AS) suggests a bidirectional relationship: TTRwt‐CA could induce AS and vice versa." (PMID 39610264, 2025). "Overall, patients with wild-type transthyretin cardiac amyloidosis (ATTRwt) may be more susceptible to AV involvement, compared to AL." (PMID 38892799, 2024). "Patients who present with cardiac disease can be evaluated for transthyretin (TTR)-associated cardiac amyloidosis using nuclear imaging with 99mTc-labeled pyrophosphate (PYP); however, light chain-associated (AL) cardiac amyloid is generally not detected using this tracer." (PMID 38578730, 2024). "Although it has been labeled as a rare disease, in recent years, transthyretin cardiac amyloidosis has stood out as an emerging cause of aortic stenosis, unexplained left ventricular hypertrophy and heart failure with preserved ejection fraction, particularly in the elderly." (PMID 39274353, 2024). "Wild-type transthyretin cardiac amyloidosis (ATTRwt) is a progressive and infiltrative cardiomyopathy caused by the extracellular deposition of transthyretin-derived insoluble amyloid fibrils, resulting in myocardial thickening and restrictive cardiac function." (PMID 39247984, 2024). "Transthyretin cardiac amyloidosis may be either caused by rare genetic mutations of the transthyretin gene in the hereditary variant, or may arise as a consequence of age-related mechanisms in the acquired form." (PMID 39274353, 2024). "In addition, musculoskeletal disorders (such as carpal tunnel syndrome, biceps tendon rupture, and low back pain) are considered a warning sign for the risk of transthyretin-associated amyloid cardiomyopathy." (PMID 39684876, 2024). "Although more than 130 amyloidogenic TTR variants have now been identified worldwide, the two which are responsible for the majority of disease-causing hATTR cardiac amyloidosis in the UK and Ireland are the V142I (formerly V122I) and T80A (formerly T60A) variants." (PMID 37653443, 2023). "However, there is increasing evidence of non-invasive diagnostic criteria for cardiac amyloidosis, especially for the transthyretin (TTR) type." (PMID 37641750, 2023). "Acoramidis (AG10) is an orally bioavailable, selective TTR stabilizer that is currently being assessed for effects on mortality and hospitalization for cardiovascular causes in subjects with transthyretin amyloid cardiomyopathy in an ongoing phase 3 trial, with topline data expected in mid-2023." (PMID 37376074, 2023). "Ttr encodes transthyretin, a protein that deposits in the heart and cause cardiac amyloidosis." (PMID 35104251, 2022). "Transthyretin amyloid heart disease could potentially be a full-fledged cause of cerebral ischemic events (mainly cardioembolic)." (PMID 35665045, 2022). "Transthyretin amyloid cardiomyopathy (ATTR-CM) is the most commonly diagnosed type of cardiac amyloidosis and may be either acquired (ATTRwt-CM) or associated with inheritance of a TTR variant (ATTRv-CM)." (PMID 36741843, 2022). "Cardiac amyloidosis (CA) is an increasingly recognized cause of heart failure (HF) and mortality, resulting from the progressive deposition of misfolded proteins, mainly immunoglobulin light chains (AL) and transthyretin (ATTR)." (PMID 34888361, 2021). "Notably, a recent study estimated that 3% of the African American population has the V122I mutation, which can cause TTR cardiac amyloidosis, and 8% of the patients suspected to have cardiac amyloidosis were reported to have pathogenic TTR mutations." (PMID 33922648, 2021).
cardiac amyloidosis (continued). "The two most common types of cardiac amyloidosis are caused by deposition of misfolded transthyretin protein, resulting in transthyretin amyloid cardiomyopathy (ATTR-CM), or by deposition of abnormal circulating immunoglobulin light chains, resulting in AL amyloidosis." (PMID 34262948, 2021). "Arthroplasty, an increasingly common procedure in outpatient settings, has been reported as an early sign of transthyretin cardiac amyloidosis (i.e., the main phenotype associated with TTR Val122Ile mutation), occurring approximately seven years before the disease diagnosis." (PMID 30813263, 2019). "Cardiac amyloidosis associated with transthyretin (TTR) is the second form ofamyloidosis with a higher prevalence of cardiac involvement, and may be dividedinto hereditary and senile forms." (PMID 28678923, 2017). "As life expectancy in the region increases, TTR V122I (pV142I) carriers may represent a cohort of individuals at substantial risk of developing clinically significant cardiac amyloidosis with aging." (PMID 27652282, 2016). "While over 20 mutations can cause TTR cardiac amyloidosis, the Val122Ile mutation (substitution of isoleucine for valine at position 122) is the most common in the United States with a particularly high frequency (prevalence of 3.4% to 3.9%) in African-Americans44." (PMID 26918183, 2016). "Moreover, emerging data suggest these agents promote favorable cardiac remodeling even in conditions like transthyretin amyloid cardiomyopathy, where SGLT2i use alongside tafamidis was associated with improved cardiac function and structure in real-world analyses." (PMID 41341359, 2025). "However, in patients with cardiac amyloidosis who present with both monoclonal gammopathies and a TTR variant, it is imperative to ascertain the tissue type of the amyloids and to employ diagnostic modalities such as Tc-99m-PYP scans to deduce the correct diagnosis." (PMID 39736876, 2024). "Therefore, we have investigated the effect of amyloid seeds, as initiators, and heparin, as surrogate for a generic physiological fibril‐stabilizer, on the fibrillogenesis of two TTR variants responsible for some of the most aggressive forms of cardiac amyloidosis, S52P and L111M TTR." (PMID 38380705, 2024). "Transthyretin cardiac amyloidosis (TTR-CA) is now increasingly becoming recognized as an important cause of heart failure, and some studies have shown that as much as a third of diastolic heart failure could be attributed to TTR-CA." (PMID 39681929, 2023). "Cardiac amyloidosis is a progressive, infiltrative cardiomyopathy, whose types are based on various infiltrating amyloids, namely, light chains in primary amyloidosis, mutated transthyretin proteins in hereditary amyloidosis, and wild-type transthyretin proteins in senile amyloidosis." (PMID 36968873, 2023). "Furthermore, there is significant phenotypic overlap in the echocardiographic, cardiac magnetic resonance, and biomarker profiles of the most prevalent cardiac amyloidosis types of AL, ATTRwt, and variant transthyretin [ATTRv], which makes proper adjudication difficult." (PMID 36982754, 2023). "The epidemiology of cardiac amyloidosis (CA), traditionally considered a rare and incurable disease, has changed drastically over the last ten years, particularly due to the advances in diagnostic methods and therapeutic options in the field of transthyretin CA (ATTR-CA)." (PMID 35884871, 2022). "GPC-4 concentrations were determined in two prospective cohorts: patients with chronic heart failure with reduced ejection fraction (HFrEF), and with transthyretin amyloid cardiomyopathy (ATTR-CM)." (PMID 41944882, 2026). "BACKGROUND AND AIM OF THE STUDY: Wild-type transthyretin cardiac amyloidosis (ATTRwt-CA) is an increasingly recognized disease in elderly individuals." (PMID 41689065, 2026).
cardiac amyloidosis (continued). "We took a systems science approach to explore the system of care for transthyretin cardiac amyloidosis testing by depicting the healthcare system from patient presentation to treatment." (PMID 41544075, 2026). "The MAGNITUDE trial evaluates NTLA-2001 in transthyretin amyloid cardiomyopathy, with cardiovascular outcomes as the primary endpoint." (PMID 41590238, 2026). "In recent years, the number of cases diagnosed with wild-type transthyretin amyloid cardiomyopathy (ATTRwt-CM) has been increasing." (PMID 41659041, 2026). "TTR depleters represent a critical advancement in the treatment of transthyretin cardiac amyloidosis." (PMID 39841315, 2025). "Our findings in the CA cohort corroborate that PYP scintigraphy (with a negative monoclonal protein screen) remains highly specific for transthyretin cardiac amyloidosis." (PMID 40943826, 2025). "Based on this highly positive Tc-99m PYP scan, TTR cardiac amyloidosis was likely diagnosed, but it was recommended to differentiate it from AL amyloidosis." (PMID 41157167, 2025). "Because of a history of bilateral carpal tunnel syndrome and polyneuropathy, the patient underwent dedicated laboratory testing and diphosphonate scintigraphy the results of which were suggestive of transthyretin cardiac amyloidosis." (PMID 40358710, 2025). "Small interfering RNA (siRNA) and antisense oligonucleotide (ASO) therapies effectively reduce TTR production and have demonstrated promising clinical outcomes, though their use in cardiac amyloidosis remains investigational." (PMID 40056371, 2025). "EMB was performed in 12/32 patients (37.5%) and revealed histological evidence of infiltrative or inflammatory CMP in 12 patients (CS in 9 patients, transthyretin (ATTR) cardiac amyloidosis in 1 patient, active lymphocytic myocarditis in 2 patients)." (PMID 40625799, 2025). "Transthyretin (ATTR) cardiac amyloidosis is an increasingly recognized disease due to the development of practical identification and effective treatment." (PMID 39917108, 2025). "Tafamidis is a transthyretin stabilizer indicated for the treatment of transthyretin amyloid cardiomyopathy." (PMID 40510111, 2025). "In line with these perspectives, the frequency of pathogenic variants in sarcomeric genes aligns with the existing literature, but TTR-related cardiac amyloidosis was notably higher, suggesting greater prevalence in this population." (PMID 41010045, 2025). "The final study population consisted of 35 patients with cardiac amyloidosis (AL‐CM: 10 patients, TTR‐CM: 25 patients)." (PMID 39873364, 2025). "In transthyretin cardiac amyloidosis (ATTR-CA), misfolded transthyretin accumulates in the myocardium, leading to wall thickening and interstitial fibrosis." (PMID 41226753, 2025). "In patients with wild-type transthyretin amyloid cardiomyopathy, hs-cTnI is a strong and independent predictor of mortality." (PMID 40371473, 2025). "We show that AI models adapted for use with POCUS can reliably identify hypertrophic cardiomyopathy and transthyretin amyloid cardiomyopathy at the point of care." (PMID 39890242, 2025). "The next challenge would be weighing the risk-benefit ratio of preoperative pacemaker implantation for patients with TTR cardiac amyloidosis." (PMID 40406766, 2025). "This study applies NAS to [18F]-Florbetaben PET cardiac images for classifying cardiac amyloidosis (CA) sub-types (amyloid light chain (AL) and transthyretin amyloid (ATTR)) and controls." (PMID 39356368, 2025). "Transthyretin (ATTR) cardiac amyloidosis has attracted clinical attention because of the development of practical identification and effective treatment." (PMID 39917108, 2025). "A 99mTc-DPD scintigraphy scan revealed Perugini grade 3 myocardial uptake consistent with wild-type transthyretin (ATTRwt) cardiac amyloidosis." (PMID 40951186, 2025).
cardiac amyloidosis (continued). "More than 98% of newly diagnosed cardiac amyloidosis is due to the deposition of fibrils composed of monoclonal immunoglobulin light chains (AL, OMIM 105200) or transthyretin (ATTR, OMIM 105210), either wild-type (ATTRwt) or mutated (ATTRm)." (PMID 41463072, 2025). "CA can be divided into two main groups: transthyretin cardiac amyloidosis (ATTR-CA) and light chain cardiac amyloidosis (AL-CA)." (PMID 41149834, 2025). "Among people of West African descent, transthyretin cardiac amyloidosis (TTR-CA) with its two main forms, wild and hereditary types, is increasingly recognized as an important cause of heart failure, accounting for nearly a third of diastolic heart failure." (PMID 39860465, 2025). "There are limited data on the prevalence and prognostic impact of significant valvular heart disease in patients with wild-type transthyretin cardiac amyloidosis (ATTRwt)." (PMID 41262632, 2025). "Typical precursor proteins that give rise to cardiac amyloidosis are immunoglobulin light chains and transthyretin, termed the AL and ATTR types, respectively." (PMID 40678255, 2025). "An improvement in LVEF to approximately 45%–50% was observed on transthoracic echocardiography, suggesting transthyretin amyloid cardiomyopathy with rhythmic involvement." (PMID 40777571, 2025). "In this issue of Current Cardiology Reports, we will review the latest advances in drug development and clinical application for clinicians managing transthyretin cardiac amyloidosis." (PMID 39841315, 2025). "In this case, we demonstrate a patient with a concurrent diagnosis of TTR cardiac amyloidosis and B-cell lymphoma that was unrelated to the cardiac amyloid." (PMID 41024906, 2025). "Moreover, for transthyretin amyloid cardiomyopathy, tafamidis could significantly decrease all-cause death or heart transplantation and endpoint (all-cause death, hospitalizations, heart failure exacerbations, heart transplant, and heart assist device implantation)." (PMID 40786045, 2025). "Technetium 99m-labeled 3,3-diphosphono-1,2-propanodicarboxylic acid (99mTc-DPD) scintigraphy showed no bone metastases but displayed significant cardiac uptake, suggesting senile transthyretin cardiac amyloidosis." (PMID 40777571, 2025). "Recently, results from the “ATTR-ACT” trial have been published, representing the first randomized study evaluating Tafamidis (commercially known as Vyndaqel) for the treatment of both wild-type and hereditary forms of transthyretin cardiac amyloidosis." (PMID 40870008, 2025). "Wild-type transthyretin (ATTRwt) cardiac amyloidosis (AL), also known as senile cardiac amyloidosis (SCA), is an underdiagnosed form of restrictive cardiomyopathy causing heart failure in elderly patients." (PMID 40777571, 2025). "For transthyretin amyloid cardiomyopathy screening using single-view parasternal acquisitions, the classifier achieved an AUROC curve of 0·919 (95% CI 0·863–0·958 for the parasternal long-axis) and 0·907 (0·874–0·932 for the parasternal short axis)." (PMID 39890242, 2025). "Transthyretin (TTR) amyloid cardiomyopathy (ATTR-CM) is a progressive disease that has emerged as a significant cause of heart failure." (PMID 40429476, 2025). "Cardiac amyloidosis, particularly transthyretin amyloid cardiomyopathy, is more prevalent in men than in women." (PMID 41001267, 2025). "Currently, over 98% of diagnosed cases of cardiac amyloidosis are attributed to fibrils composed of either monoclonal immunoglobulin light chains (AL) or transthyretin (ATTR), which can occur in hereditary (ATTRv) or acquired (ATTRwt) forms." (PMID 40427056, 2025). "Keywords such as “cardiac amyloidosis”, “cardiac amyloidosis from transthyretin”, “cardiomyopathy”, “transthyretin”, “immunoglobulin light-chain amyloidosis”, and “familial amyloidosis” were used." (PMID 40427056, 2025).
cardiac amyloidosis (continued). "Particular attention should be given to elderly patients with left ventricular hypertrophy to rule out potential concomitant red flags, which are crucial to avoid failing to diagnose the increasingly prevalent transthyretin wild-type cardiac amyloidosis." (PMID 40142790, 2025). "Wild-type transthyretin cardiac amyloidosis (ATTRwt CA) is increasingly recognized as an important cause of heart failure and arrhythmias in older people." (PMID 40358710, 2025). "Little is known about its application in patients with wild-type transthyretin amyloid cardiomyopathy (wtATTR-CM)." (PMID 40392471, 2025). "A 99mTc-DPD nuclear scan was arranged to evaluate for transthyretin-related (ATTR) cardiac amyloidosis." (PMID 40951186, 2025). "For instance, “ATTR-CM”, “ATTR-CA”, “transthyretin cardiac amyloidosis”, and “ATTR cardiomyopathy” were merged into “transthyretin amyloid cardiomyopathy”." (PMID 40093801, 2025). "Transthyretin cardiac amyloidosis (ATTR-CA) involves the buildup of transthyretin protein in the heart muscle in the form of amyloid fibrils, which can affect heart structure and function." (PMID 40070618, 2025). "Apical sparing phenomenon was more remarkable in transthyretin amyloid cardiomyopathy (TTR‐CM) than amyloid cardiomyopathy (AL‐CM)." (PMID 39873364, 2025). "There are few data on the prognostic impact of pulmonary-right ventricular (RV) uncoupling in patients with wild-type transthyretin amyloid cardiomyopathy (ATTRwt-CM)." (PMID 39831277, 2025). "The aim of the present study was to elucidate the differences in speckle tracking echocardiographic findings between immunoglobulin light chain amyloid cardiomyopathy (AL‐CM) and transthyretin amyloid cardiomyopathy (TTR‐CM)." (PMID 39873364, 2025). "One of the patients was a gentleman who had transthyretin (ATTR) cardiac amyloidosis and developed high-grade AVB." (PMID 40422935, 2025). "Over 98% of cardiac amyloidosis are due to two main types: light chain cardiac amyloidosis (AL) and transthyretin (TTR) which at the same time is subdivided in two entities, hereditary and wild-type." (PMID 39857728, 2025). "He subsequently underwent an endomyocardial biopsy that confirmed ATTR (transthyretin)-type cardiac amyloidosis." (PMID 41024906, 2025). "The final study population consisted of 50 patients with a confirmed diagnosis of cardiac amyloidosis, 21 patients having AL‐CM, and 29 patients with TTR‐CM." (PMID 39873364, 2025). "In transthyretin amyloid cardiomyopathy (ATTR-CM), TTR builds up in the heart and affects the heart muscle, as well as the nerves and other organs." (PMID 40725383, 2025). "Our vignette emphasized the early utilization of different cardiac imaging modalities to unravel the diagnosis of transthyretin cardiac amyloidosis." (PMID 40134993, 2025). "Across both sets, 46 398 (16·0%) videos corresponded to hypertrophic cardiomyopathy, 8842 (3·0%) to transthyretin amyloid cardiomyopathy, 41 465 (14·3%) to severe aortic stenosis, and 193 952 (66·8%) were used as controls." (PMID 39890242, 2025). "Similar findings denoting the higherprevalence of AF in TTR cardiac amyloidosis were reported by Cyrille etal." (PMID 41524065, 2025). "ATTRUBY (acoramidis) is a transthyretin stabilizer approved by the FDA on 22 November 2024 for treating wild-type or hereditary transthyretin-mediated amyloid cardiomyopathy (ATTR-CM) in adults to reduce cardiovascular mortality and hospitalization risks." (PMID 41304751, 2025). "Another multicenter RCT randomly assigned 441 individuals with transthyretin amyloid cardiomyopathy." (PMID 40786045, 2025). "In the examples shown for hypertrophic cardiomyopathy, the signal localised to the left ventricle, whereas for transthyretin amyloid cardiomyopathy, the signal extended to the left atrium." (PMID 39890242, 2025).